CD4 (CD4 molecule)
Diseases named in the same sentence as CD4 in open-access papers (continued):
Sharing a sentence is not in itself a finding about the gene and the disease.
tumor (continued). "This microbial modulation enhances immune activation by increasing key immune cell populations such as CD8+, CD4+, and FOXP3+ T-cell populations, which are critical for effective anti-tumor immunity." (PMID 41424605, 2025). "The combination treatment with TTFields and anti-PD-1 facilitated more infiltration of CD3+, CD4+ and CD8+ T cells into both the periphery and center of the tumor tissue, than anti-PD-1 treatment alone." (PMID 40098106, 2025). "In terms of infiltrating immune cell distribution, CD20+ B cells, CD8+ T cells, CD4+ T cells, and CD4+ FoxP3+ Treg cells were mainly distributed in the stroma, whereas CD68+ macrophages were concentrated in the tumor parenchyma." (PMID 40710213, 2025). "Our analysis demonstrated that both CD4+ and CD8+ T cell subpopulations are indispensable for mediating tumor elimination in tumor-bearing mice receiving HVEM-Fc treatment." (PMID 39979981, 2025). "T cell subsets such as CD4+ helper T cells (Th) and CD8+ cytotoxic T cells are involved in immune regulation and direct killing of tumor cells, respectively." (PMID 40612858, 2025). "They analyzed the spatial distribution of (CD3, CD4, CD8), B cells (CD20), macrophages (CD16), and tumor cells (K17)." (PMID 40909977, 2025). "Flow cytometry confirmed the substantial activation of both CD4+ and CD8+ T cells, while apoptosis assays showed selective tumor cytotoxicity (>55% tumor apoptosis) with minimal impact on non-malignant cells (>92% viability)." (PMID 40427155, 2025). "However, using a spontaneous lung adenocarcinoma model, a study showed that naive tumor-specific CD4+ T cells activated and underwent proliferation in the tdLN do not differentiate into effectors, as they either become Tregs or enter a state of anergy from the early stage of tumor development." (PMID 41030446, 2025). "Treatment with CB + miR + R/PGA-SLN-CSW increased cytotoxic (CD8+) and helper (CD4+) T cell populations, reduced FoxP3+ regulatory T cells, and depleted CD206+ M2-type TAMs within the tumor and/or spleen." (PMID 41304839, 2025). "Immunohistochemical analysis quantified CD4+, CD8+ T cells, and CD56+ NK cell infiltration in paired pre- and post-treatment tumor tissues." (PMID 40936903, 2025). "When mimics of these miRNAs are transfected into CD4+ T cells, they induce an imbalance in Treg/Th17 cell populations via STAT3 signaling, leading to an immunosuppressive microenvironment at the tumor site, which facilitates tumor progression and metastasis." (PMID 40612677, 2025). "The findings showed that MBP nanoemulsions successfully prevented tumor development and lung metastasis by inducing immunogenic cell death (ICD) and CD8+/CD4+ T-cell activation." (PMID 40872479, 2025). "In this study, we investigated the distribution of TIM-1 on CD4+ T cells, CD8+ T cells, and B cells in the tumor primary lesion and TDLN for the first time." (PMID 40519901, 2025). "Within the tumor microenvironment (TME), the early stages are characterized by a predominance of M1 macrophages, NK cells, and CD4+/CD8 + T cells, which secrete anti-tumor factors including IL-2, IL-12, IL-18, and IFN-γ." (PMID 41384115, 2025). "The intracellular expression of the transgene(s) facilitates the processing of the tumor antigen via both class I and II MHC pathways, resulting in the activation of CD4 + and CD8 + T cells." (PMID 40167762, 2025). "Multiple immune cell markers were evaluated, including T cell markers, CD3, CD4, CD8; the macrophage marker CD68; CK-SOX10 tumor marker; and immune modulatory factors, PD1, PDL1, FOXP3, IFN-γ, NOS2, and COX2." (PMID 40663402, 2025). "CD4+ T28zT2 T cells upregulated NKG2D within tumors and suppressed tumor growth by producing IFN-γ and Granzyme B. Previous studies consistently report that TGF-β1 suppresses the expression of NKG2D in T cells and NK cells." (PMID 40107245, 2025).
tumor (continued). "These were combined with paired TCRs from 9,341 CD4+ and 4,935 CD8+ intratumoral T cells (50.4% and 53.9%, respectively, of all tumor T cells with RNA data) from the same patients." (PMID 40299576, 2025). "According to reports, a thermo-sensitive hydrogel co-loaded with DOX/IL-2/IFN-γ improved B16F10 melanoma tumor response to treatment by enhancing tumor cell death and boosting CD3+/CD4+T and CD3+/CD8+T cell proliferation." (PMID 40430316, 2025). "The results demonstrated that oAd-SA increased CD3+, CD4+ and CD8+ T cells percentage in all viable cell digested from MC38 tumor tissue compared with mice giving PBS." (PMID 40070841, 2025). "In the primary dataset, there was a greater frequency of signaling from malignant cells, Treg cells, CD4+ T cells, and CD8+T cells to macrophages, indicating directional interactions between these cell types in the primary tumor context." (PMID 40858590, 2025). "The IHC results further demonstrated the more the CCR8+ cell infiltration, the less the presence of CD45+ immune cells, CD4+ cells, CD8+ cells, as well as CD56+ cells in the tumor tissues." (PMID 40186298, 2025). "We then compared CD4 and CD8 T cells co-expressing either CD25 or PD-1, NK cells (CD3−/DX5+), NKT cells (CD3+/DX5+), and B cells (CD19 cells) in the different tumor groups." (PMID 40457031, 2025). "Regulatory T cells (Tregs), identified as CD4+FOXP3+CD25high T cells, play an important role in regulating tumor immunity." (PMID 40860134, 2025). "In vivo experiments demonstrated that BN1 effectively reduced tumor burden while exhibiting immunostimulatory effects, including the increase of CD8+ IFNγ+ cells, the decrease of CD4+ Foxp3+ cells, and the regulation of cytokines." (PMID 40885393, 2025). "In a melanoma model, TCR-transgenic CD4+ T cells (gDT-II) infiltrated tumors and interacted with MHC II+ antigen-presenting cells carrying tumor debris, suppressing or eradicating tumors independently of other lymphocytes." (PMID 40995371, 2025). "Cells isolated from the spleens and tumor tissues were stained for surface markers (CD45, CD3, CD4, and CD8) and intracellular markers (granzyme B, IFN-γ, TNF-α, and FoxP3)." (PMID 40969744, 2025). "Consistent with our findings, a previous study identified a correlation between advanced tumor stage, poor prognosis, and a high percentage of TIM-3-positive CD4+ and CD8+ T cells indicating immune cells as a potential cellular source for its soluble form." (PMID 41323263, 2025). "Several studies have shown that the combination of Montanide with the peptides of the oncoproteins E6 and E7 stimulates both CD4+ and CD8+ T lymphocytes, favoring a more robust and tumor-directed immune response." (PMID 40006583, 2025). "Tumor sections were stained with hematoxylin and eosin (H&E) and immunohistochemistry (IHC) with CD3, CD4, and CD8 antibodies." (PMID 40067762, 2025). "We observed that simultaneous depletion of both CD4+ and CD8+ T cells resulted in a much stronger rescue of tumor growth in Uba1-depleted tumors." (PMID 39540840, 2025). "It has been reported that cDC1 is primarily responsible for cross-presenting tumor antigens to naïve CD8+ T cells, generating cytotoxic T lymphocytes (CTLs), whereas cDC2 can present exogenous antigens via MHCII to CD4+ T cells." (PMID 40573908, 2025). "Activates WT1‐specific CD4+/CD8+ T cells, modulates the tumor microenvironment, and reduces Treg cells and MDSCs." (PMID 41200280, 2025). "Relative to mismatch repair deficient (dMMR) colorectal cancers, which are an archetype of an ICI-responsive tumor rich in TLSs, we found that HGG PCa was similarly infiltrated by B cells but had fewer CD4+ and CD8+ T cells." (PMID 41000797, 2025). "In a humanized mouse model of lung cancer, vaccination with iPSCs and CpG led to an increase in splenic APCs, cytotoxic T cells, circulating effector/memory CD4+ and CD8+ T cells, and tumor-infiltrating CD8+ T cells, while reducing regulatory T cells (Tregs)." (PMID 39995659, 2025).
tumor (continued). "Markers included CD4+ (helper T cells), CD8+ (cytotoxic T cells), CD11c+ (dendritic cells), TCRγ/δ+ (γ/δ T cells), ATRX+ (tumour cells) and DAPI+ (nuclei), with STING as a primary marker of interest." (PMID 39856469, 2025). "CD8+ T cells are essential for recognizing and eliminating tumor cells via MHC I, while CD4+ T cells, specifically Th1 cells, activate CD8+ T cells and NK cells to enhance antitumor activity 34-36." (PMID 39781341, 2025). "TCR signaling cleaved Gasdermin D to form GSDMD-N pores in the plasma membrane of CD4+ T cells, which triggers Ca2+ influx to induce the expression of IL-2 to aid CD8+ T-mediated tumor cell killing." (PMID 40759573, 2025). "IF revealed minimal CD4+ cells at the tumor periphery and sparse CD8+ cells in partial responders, in contrast to strong CD4+ staining in scar-like tissues and substantial CD4+/CD8+ T cell accumulation throughout pancreatic tissues in responders." (PMID 41041061, 2025). "In a breast cancer mouse model treated with low-dose cyclophosphamide combined with CSF1R inhibitors, CD4+ T cells and antigen-presenting B cells were enriched and colocalized in the TLS, inducing the durable tumor regression after combination treatment." (PMID 39744696, 2025). "A glycogen (SEP) extracted from S. nudus inhibited tumor growth in mice by up-regulating the phosphorylation and transcription levels of ERK in spleen, promoting splenocyte proliferation and increasing CD4+ and CD8+ T cell numbers." (PMID 40786029, 2025). "In our study, we found that CD4 Treg, CD8-Tem-PDCD-1, and CD8-Temra levels gradually increased during tumor progression." (PMID 39354287, 2025). "To explore the effect of triple therapy on immune cell subsets, we obtained lung metastatic nodal tissues from tumor-bearing mice and stained them with the T cell markers CD3, CD4, and CD8." (PMID 40109871, 2025). "The concurrent increase in CD8+ and CD4+ T cell populations and reduction in PD-L1 and TAM markers in tumor and spleen tissues indicates reversal of the TAM-enriched TME." (PMID 41304839, 2025). "CD4+ T cells regulate CTL activation and secrete cytokines and chemokines that support anti-tumor immunity." (PMID 40264780, 2025). "Anti-CCR8 antibody therapy, targeting tumor-infiltrating CCR8+ Tregs, has the potential to restore the function of CD4+ Th and CD8+ T cells in CRC, thereby inducing antitumor immunity." (PMID 40308582, 2025). "Compared with baseline tissues, the density of CD4 + and CD8 + T cells in the tumor microenvironment of the on-treatment tissues decreased, but the expression of IFN-γ in CD4 + and CD8 + T cells increased." (PMID 40411616, 2025). "Following the injection of sh-TBX21, no significant changes were observed on the clusters of PD-1+CD4+ T cells, Tim-3+CD4+ T cells, Lag-3+CD4+ T cells, PD-1+CD8+ T cells, Tim-3+CD8+ T cells, and Lag-3+CD8+ T cells in tumor tissues." (PMID 41573646, 2025). "This help was driven by alloreactive CD4+ Th cells recognizing mutant MHC class II molecules, resulting in the expansion of effective CD4+ Th cells and reduction in Tregs in the TC-1 tumor model in vivo and vitro." (PMID 40857404, 2025). "The immune microenvironment, particularly CD4+ T-helper cells and FOXP3 (forkhead box P3)+ regulatory T cells (Tregs), plays a crucial role in tumor progression." (PMID 41007768, 2025). "The TIGIT protein is overexpressed on immune cells, such as CD4+ and CD8+ T cells, but also natural killer (NK) cells, having an essential role in immunosuppression, especially through interaction with the tumor microenvironment (TME)." (PMID 40277786, 2025). "The results showed that the number of CD4+ and CD8+ T cells within the tumor tissue of mice treated with LPS was higher than that in the untreated tumor tissue, indicating the immunostimulatory effect of LPS." (PMID 39799561, 2025). "Meflin-positive CAF enhanced the tumor response to immune checkpoint blockade (ICB) therapy, positively correlating with CD4+ T-cell infiltration and vascularization." (PMID 40244052, 2025).
tumor (continued). "CD8+LAG-3−PD-1+TIM-3−, CD4+PD-L1+, and CD4+FoxP3− T cell densities were significantly higher in the TLS within TC compared to tumour and stromal regions." (PMID 39901202, 2025). "Both age cohorts had similar numbers of CD8+ tumor-infiltrating lymphocytes (TILs), although LAO patients had more CD4+ TILs and Th1-polarized CD4s." (PMID 39980836, 2025). "However, different subpopulations of CD4+ T cells, such as Th1, Th2, and Th17, are highly plastic within the tumor microenvironment and may exert opposing effects, either promoting or suppressing anti-tumor responses." (PMID 41394802, 2025). "Our findings indicated that the knockdown of PRMT5 in the tumor microenvironment resulted in increased levels of IFN-γ and TNF-α expression in both CD4+ and CD8+ T cells." (PMID 41463372, 2025). "Panel 6 assesses PD1, PD-L1, and TIM-3 specifically as expressed on immune cells (CD4+PD-1+, CD4+TIM-3+, CD8+PD-1+ and CD8+TIM-3+) and tumour cells (SYN+PD-1+, SYN+TIM-3+ and SYN+PD-L1+)." (PMID 41285059, 2025). "Our findings indicate that fibroblasts impede the anti-tumor immune response mediated by C1QC+ RTMs and CD4+ T cell pairs." (PMID 40593467, 2025). "Ever smoking, compared to never smoking, was associated with poorer CC-specific survival among individuals with lower densities of CD3+, CD4 +, and FOXP3 + tumour-infiltrating immune cells." (PMID 41631717, 2025). "T cells play a critical role in anti-tumor efficacy, and we found that the proportion of CD3+ and CD4+ T cells was slightly increased in the OVA&si-Irg1-LNP group compared to that in the OVA-LNP group." (PMID 40521193, 2025). "The proportion of tumor-infiltrating CD4 + and CD8 + T-cells was increased in Ubr5−/− tumor-bearing mice compared to control tumors." (PMID 39857943, 2025). "At lower %sO2, where oxygen unloading into the tumor TME was greater, we observed greater frequencies of CD8 and CD4 + FoxP3- effector T cells (Teffs) in CT26 tumors." (PMID 40594309, 2025). "For instance, tumor-reactive CD4+ T cells can induce tumor rejection in mouse models when transplanted and treated with anti-CTLA-4, demonstrating that cytotoxic CD4+ T cells can directly target and destroy tumor cells." (PMID 40177538, 2025). "Significantly, to support anti-tumor immunity against tumor cells, lncRNAs can encourage the infiltration of immune cells such as B cells, T cells (including CD8 + and CD4 + T cells), neutrophils, and dendritic cells." (PMID 39825964, 2025). "In MC38-tumors in mice, MATE-expression by the oncolytic adenovirus Ad5/11 facilitated intratumoral T-cell activation, reduced tumor growth and prolonged survival accompanied by infiltration of tumor-directed CD8+ T cells and improved CD8/CD4 T-cell ratio." (PMID 39789356, 2025). "In summary, HPV-infected tumor cells evade host adaptive immunity through multiple mechanisms, including downregulating MHC molecules, suppressing CD4+ T cells, inducing regulatory T cells, and disrupting signaling pathways, thereby facilitating tumorigenesis." (PMID 40264780, 2025). "Coculturing creates a population of CD4+ and CD8+ T cells at a 1:1 ratio, which improves upon the expansion, phenotype, and in vivo anti-tumor activity of CAR T cells compared to isolated cultures of CD8+ T cells." (PMID 40861448, 2025). "For effective peptide tumor vaccines, their anti-tumor mechanism of action depends on activated CD8+ and CD4+ T cells." (PMID 40733649, 2025). "The results showed that CD19‐81‐293‐EXO treatment recruited similar levels of CD45+ leukocytes; CD68+ macrophages and monocytes; CD11c+ dendritic cells; and CD3+, CD4+, and CD8+ T cells into the tumor compared to the control group." (PMID 40985609, 2025). "IL-12, for example, promotes the differentiation of naïve CD4+ cells into type 1 T helper cells (Th1) and enhances CD8+ cytotoxic T cells (CTLs) and natural killer (NK) cells in their anti-tumor responses." (PMID 40699676, 2025).
tumor (continued). "PD-1+Tim3+ cells were increased in CD4+CD44+/CD8+CD44+T cells, indicating that the CD4+ and CD8+ T cells with exhaustion phenotype were predominantly present in tumor nodules." (PMID 40777028, 2025). "For several tumor types, CD8+, CD4+, and CD20+ cell levels have been shown to positively correlate with oncologic prognosis." (PMID 41463008, 2025). "High NETs signature group patients exhibit a significant presence of anti-tumor immune cells in the TME, such as NK cells, CD8+ T cells, and CD4+ T cells." (PMID 40988926, 2025). "The results confirmed that, compared to the pLCR group, the tumor and lymph node tissues of the nLCR group had significantly higher infiltration of regulatory T cells (CD3+ CD4+ FOXP3+)." (PMID 40759637, 2025). "Markers for T-cell subsets (CD4, CD8), macrophages (CD68, CD163), granulocyte cells (CD11b), tumor cells (PanCK), vasculature (CD31), and epithelium (cytokeratin) were clearly visualized in the CODEX fluorescent images." (PMID 39969434, 2025). "The anti-tumor effect of aCD40 effect was cDC1 and CD8 + T cell-dependent, whereas the rejection of secondary tumor rechallenge in cured mice required CD4 + T cells." (PMID 40585246, 2025). "Importantly, characterization of CD4+ and CD8+ T cell subpopulations in vitro showed that PTSO was able to increase those producing IFNG, thus resulting in an increase in Th1 and Tc1 subsets, which are reported to be linked to a reduction in tumor progression in CRC." (PMID 41010517, 2025). "Dendritic cells can be loaded with tumor antigens (e.g., tumor lysates, peptides, or RNA) and administered to the patient to stimulate both CD4+ and CD8+ T cell responses, which are critical for targeting and eliminating tumor cells." (PMID 39936958, 2025). "Antigen-presenting dendritic cells regulate anti-tumor immune responses by activating CD8 and CD4 positive T lymphocytes through the Major Histocompatibility Complex." (PMID 40075893, 2025). "The results revealed that, in addition to tumor cells, TIM-1 is also expressed on CD4+ T cells, CD8+ T cells, and B cells within both the tumor primary lesion and TDLN." (PMID 40519901, 2025). "The results demonstrated significant infiltration of both SIGLEC9+ CD4+ T-cells and SIGLEC9+ CD8+ T-cells in the tumor microenvironment." (PMID 41418390, 2025). "Immune checkpoint inhibitors modulate the interaction between immune cells, including CD4+ and CD8+ T-cells, B-cells, macrophages, dendritic cells (DCs), tumor-infiltrating lymphocytes (TILs), and tumor cells." (PMID 40422248, 2025). "B cells capture and process tumor antigens via their surface B cell receptors (BCR) in the TDLNs, and present antigens to CD4+ T cells through MHC II proteins, thereby activating T cell-mediated immune responses." (PMID 40904508, 2025). "Concomitant with tumor control, we observed changes in the tumor microenvironment, including a reduction in α-SMA+ pericytes and an increase in the infiltration of CD4+ and CD8+ T cells." (PMID 41488668, 2025). "It enhances the infiltration of CD3+, CD4+, and CD8+ T cells, invigorating the immune response at the site of the tumor." (PMID 40070841, 2025). "The distance between CD11b+/CD15+ granulocytes and tumor cells, as well as both CD8+ and CD4+ T-cell subsets, was reduced as compared to IDH1+ iCCA and FGFR2 WT/IDH1 WT iCCA (p<0.001 for all comparisons)." (PMID 39969434, 2025). "Intratumoral immune effector cells (such as CD4+ and CD8+ T cells) create an anti-tumor inflammatory microenvironment that inhibits tumor growth early in tumor progression." (PMID 41293265, 2025). "DCs are professional antigen-presenting cells (APCs) that bridge innate and adaptive immunity by recognizing tumor or viral antigens and activating naïve CD8+ and CD4+ T-cells." (PMID 41303704, 2025). "Our results show that UCEC’s low-SMARCAL1 group has larger amounts of CD8 T cells, while other tumor types often have lower levels of CD8 and CD4 T cells." (PMID 39994264, 2025).